ETS2 (ETS proto-oncogene 2, transcription factor)
Diseases named in the same sentence as ETS2 in open-access papers (continued):
Sharing a sentence is not in itself a finding about the gene and the disease.
Down syndrome (14 papers, 2010 to 2024). "The ETS2 gene encodes a transcription factor that regulates numerous genes and is overexpressed in the brain and fibroblasts of Down syndrome (DS) individuals." (PMID 30477169, 2018). "ETS2 is a transcriptional regulator of the β-amyloid precursor protein, which is centrally involved in senile plaque formation in Down syndrome and AD." (PMID 38107644, 2023). "Increased dosage of Ets2 led to skeletal abnormalities similar to trisomy-16 mice and Down’s syndrome in human." (PMID 36383615, 2022). "Ets-2 has also been found to have a tumor suppressor role in a mouse model of Down syndrome in which enhanced Ets-2 activity induced significant inhibition of intestinal tumors." (PMID 29354130, 2017). "Notably, three genes outside of the deletions (JAM2, ADAMTS1, and ETS2) and within the Down syndrome critical region (DSCR) were downregulated in RD_P26 NESCs when compared to euploid NESCs." (PMID 35186010, 2021). "However, studies on various mouse models (including models of Down's syndrome, in which three copies of ETS2 exist) have revealed that ETS2 can also repress tumor growth, and this would support a positive role of the kinase in regulating cell proliferation and tumorigenesis." (PMID 28178678, 2017). "Neurogenesis-related genes such as DYRK1A and RCAN1, craniofacial defect-related genes such as DYRK1A, ETS2, and RCAN1, and tumor suppressor-related genes such as DYRK1A, ETS2, and RCAN1 were also reported in Down syndrome." (PMID 34433490, 2021). "Expression levels of Down syndrome-related genes such as SOD1, DYRK1A, ETS2, APP, and DSCR1 in chromosome 21 are comparable with the gene number, i.e., three 21 chromosomes." (PMID 30760866, 2019). "ETS2, one of the members of the ETS family as ERG, was previously characterized as a proto-oncogene in AMKL children that is Down-syndrome and non-Down-syndrome-related, but the expression and clinical prognosis of ETS2 in AML remains unknown." (PMID 28724426, 2017).
colon cancer (10 papers, 2007 to 2026). "RuvBl2 can cooperate with Ets2 to regulate the transcription of hTERT in colon cancer, and enhance tumor cell viability in HCC." (PMID 27509054, 2016). "Our results are consistent with those of a previous study in which overexpression of ETS2-DN and Elk1-DN significantly decreased the P5 promoter activity in colon cancer cells." (PMID 23840432, 2013). "Thus, while frequently overexpressed in colon cancer, at least some Ets factors, including Ets2 and those blocked by the En/Erm transgene in our studies, appear to normally restrict, rather than promote, epithelial neoplasia in the intestine." (PMID 19545444, 2009). "Strikingly, most of the Wnt genes upregulated by HMGA1 in our murine model are also upregulated in human colon cancer, including the WNT effectors, ASCL2, AXIN2, CTNNB1, MYC, EPHB2, CD44, and ETS2 and the WNT receptors, LGR5, LRP5, and LRP6." (PMID 39895630, 2025). "Furthermore, it was demonstrated that the p42 splice variant of ETS1 can cause human colon cancer cells to undergo apoptosis, and that the survival of thyroid carcinoma cells, but not normal thyroid cell lines, depends on the activity of the ETS1 and ETS2 proteins." (PMID 39941022, 2025).
gastric cancer (10 papers, 2016 to 2025). A primary or metastatic malignant neoplasm involving the stomach. "In gastric cancer, amplification of ETS2 (21q22.3) promotes tumor proliferation by activating the RAS/MAPK pathway, and it has also been associated with chemotherapy resistance." (PMID 40963872, 2025). "ETS2 regulates microRNA-126 in endothelial cells 72, stimulates miR-155 during the inflammatory response 73, and represses the expression of miR-196b in gastric cancer cells 74 by binding to motifs containing the conserved sequence GGAA on the promoter." (PMID 31754329, 2019). "In this study, we identified that the carcinogenic bacterium H. pylori increased ETS2 transcription factor-mediated Siah1 protein expression in gastric cancer cells (GCCs) MKN45, AGS and Kato III." (PMID 28481365, 2017). "An association between ETS2 and TWIST1 was also confirmed in Helicobacter pylori-infected gastric cancer cells (GCCs), where the two genes were found to enhance SIAH2 expression." (PMID 29299035, 2017). "ETS2 can affect the progression of osteosarcoma and gastric cancer." (PMID 36536279, 2022). "As Siah1 lacks Twist1-binding site, we speculate that these isotypes can still be differentially regulated since ETS2 and Twist1 expression might vary depending on the staging of gastric cancer." (PMID 28481365, 2017). "The level of mRNA expression of ETS family members in gastric carcinoma tissues was also variable with ELF3, ETS2, EHF, ERF and ELF1 being the family members with the highest expression." (PMID 41425714, 2025). "mRNA expression levels of ETS family members in gastric carcinoma tissues were variable, with ELF3, ETS2, EHF, ERF, and ELF1 being the family members with the highest expression." (PMID 41425714, 2025). "Induced expression of ETS2, Twist1 and Siah2 was found in gastric cancer biopsies compared with noncancerous gastric tissue." (PMID 33825941, 2021). "In the gastric cancer cells AGS, Kato III and MKN45, H. pylori infection induced an expression of Siah2, in a E26 transformation-specific sequence 2 (ETS2)- and Twist-related protein 1 (Twist1)-dependent manner, which was accompanied by increased invasiveness and migration." (PMID 33825941, 2021).
bladder cancer (7 papers, 2013 to 2025). "The role of Ets-2 in bladder cancer is unclear, thus we verified the functional consequence of Ets-2 knockdown in bladder cancer cells." (PMID 24069250, 2013). "MiR-663b generated from exosomes of bladder cancer cells could act as a tumor promoter via targeting Ets2-repressor factor." (PMID 37805491, 2023). "MicroRNA(miR)-663b was found increased in plasma from patients with bladder cancer (BC), while it could promote epithelial-mesenchymal transition via targeted Ets2-repressor factor." (PMID 37805491, 2023). "To determine whether suppression of Ets-2 induce apoptosis in bladder cancer cells via Akt pathway, a privotal apoptosis regulator pathway, we investigated the protein expression level of total Akt and phosphorylated Akt (pAkt)." (PMID 24069250, 2013). "Taking into account the anti-apoptosis function of Ets-2, our data suggested that Ets-2 regulates apoptosis process by regulating the expression of UCA1, moreover UCA1 may be involved in the activation of Akt signaling pathway by Ets-2 in bladder cancer cells." (PMID 24069250, 2013). "Although there are data supported that Ets-2 takes part in bladder cancer development, the exact roles and mechanisms of Ets TFs in bladder cancer are mostly unknown." (PMID 24069250, 2013). "Thus we assumed that UCA1 gene expression may be associated with the activation of Akt pathway which is involved in the Ets-2 mediated anti-apoptosis process in bladder cancer cells." (PMID 24069250, 2013). "Previous reports showed that miR-146b-5p was involved in developing multiple human cancers, such as nasopharyngeal carcinoma and bladder cancer, targeting functional genes, such as MMP2 and ETS2." (PMID 34332611, 2021). "To test whether Ets-2 regulates Akt pathway through UCA1, we used another bladder cancer cell line BLS-211, which lacks of UCA1 gene expression and it is derived from the same patient as BLZ-211." (PMID 24069250, 2013). "Further analysis of this site by gel shifting, chromatin immune precipitation (ChIP), and co-transfection experiments showed that transcription factor Ets-2 directly bound to the UCA1 promoter region and stimulated UCA1 promoter activity in bladder cancer cells." (PMID 24069250, 2013).
lung carcinoma (7 papers, 2013 to 2023). "Further, ETS2 may reduce TERT promoter activity in lung cancer cells in an allele-specific manner." (PMID 28978027, 2017). "However, our study provides functional evidence for the association of ETS2 rs461155A>G with clinical outcomes by showing its strong correlation with ETS2 mRNA expression in clinical samples as well as in vitro assays using lung cancer cell lines, which supports the credibility of the association." (PMID 26893365, 2016). "KM Plotter showed that low levels of ETS2 and RCAN1 are associated with poor survival outcomes in breast and lung cancers." (PMID 37107558, 2023). "The associations between ETS2 and RCAN1 and patient survival in breast and lung cancers were investigated using KM Plotter." (PMID 37107558, 2023). "In conclusion, ETS2 and RCAN1, which are significantly upregulated in DS mouse models, are downregulated in human breast and lung cancers and are associated with patient survival." (PMID 37107558, 2023). "Future studies are needed to confirm our findings and to understand the biologic function of ETS2 in the development and progression of lung cancer." (PMID 26893365, 2016). "Further investigation is needed to understand the role of ETS2 in lung cancer and the mechanism of its dissimilar effects on the prognosis of patients in different stages undergoing different anticancer therapy." (PMID 26893365, 2016). "From our analyses, ETS2 levels were associated with patient survival but not cancer stage, suggesting that ETS2 is associated with the development but not the progression of breast and lung cancers." (PMID 37107558, 2023). "In this in silico study, we identified two DSCR genes (ETS2 and RCAN1) that are upregulated in DS mouse models but are significantly downregulated in human breast and lung cancer tissues compared to normal tissues and are associated with cancer patient survival." (PMID 37107558, 2023). "The GO analyses for cellular components and molecular function showed that ETS2 is involved in the positive regulation of immunological synapses and the negative regulation of odorant binding and olfactory receptor activity in breast and lung cancers." (PMID 37107558, 2023). "These signaling pathways have been shown to affect the development and progression of breast and lung cancers, suggesting that ETS2 may contribute to the biology and immune landscape of breast and lung cancers." (PMID 37107558, 2023). "Considering their expression patterns in DS and breast and lung cancers, as well as their co-expression in these cancers, we hypothesize that ETS2 and RCAN1 are at least partly responsible for the low incidences of breast and lung cancers in DS." (PMID 37107558, 2023). "EGFR activates miR-7 through the Ras/extracellular signal-regulated kinase (ERK)/Myc pathway and inhibits ETS2 repressor factor (ERF, a transcriptional repressor of V-ets avian erythroblastosis virus E26 oncogene homolog 2 (Ets2)), thereby promoting cell growth and the occurrence of lung cancers." (PMID 30400981, 2018). "Notably, functional evidence for ETS2 rs461155A>G was provided by ETS2 mRNA expression in clinical samples, which was further supported by in vitro assays using lung cancer cell lines." (PMID 26893365, 2016). "In addition, in vitro luciferase assay suggested that the ETS2 rs461155 A-to-G change could alter binding efficiency of miR-149 to ETS2 mRNA, leading to decreased ETS2 mRNA expression level and better clinical outcomes of lung cancer." (PMID 26893365, 2016). "ETS2, an ETS transcription factor family oncogene, inhibits lung cancer cells’ growth, migration, and invasion by suppressing mesenchymal-epithelial transition (MET) expression." (PMID 37745301, 2023). "Thus, ETS2 may at least partially protect DS individuals from developing lung cancer." (PMID 37107558, 2023). "In this study, a positive correlation between ETS2 and RCAN1 was observed in breast and lung cancers." (PMID 37107558, 2023).
lung carcinoma (continued). "Similar results were observed in the lung cancer cohort, suggesting that ETS2 and RCAN1 expression affect survival outcomes in breast and lung cancers." (PMID 37107558, 2023). "Another study discovered that in breast and lung cancers, ETS2 amplification (but not deletion) is the only type of genetic alteration." (PMID 37107558, 2023). "This suggests that ETS2 and RCAN1 are co-expressed and may possess complementary functions in the development of breast and lung cancers." (PMID 37107558, 2023). "Altogether, ETS2 and RCAN1 may be essential for the development of breast and lung cancers." (PMID 37107558, 2023). "Of these genes, ETS2 and RCAN1 were determined to be significantly downregulated in both cancers, suggesting that they may act as tumor suppressors against breast and lung cancers." (PMID 37107558, 2023). "However, the biologic mechanism of the observed association between the SNP and the clinical outcomes remains unclear because the role of ETS2 in lung cancer has not been fully elucidated." (PMID 26893365, 2016). "Similarly, ETS2 and RCAN1 expressions were not influenced by lung cancer stages." (PMID 37107558, 2023).
acute myeloid leukemia (5 papers, 2017 to 2023). Acute myeloid leukemia (AML) is a group of neoplasms arising from precursor cells committed to the myeloid cell-line differentiation. "ETS2 and PML-RARA are a protooncogene and a protein resulting from a chromosomal translocation that generates an oncofusion protein, respectively, having both been linked to acute myeloid leukemia." (PMID 36855161, 2023).
breast tumor (5 papers, 2013 to 2025). "Previous work demonstrates that Ets2 function in stromal cells significantly contributes to breast tumor progression." (PMID 23977064, 2013). "Depletion of ETS2 in TAMs reduces metastasis in mouse breast tumor models." (PMID 36483544, 2022). "Targeting Ets2-dependent DNA and histone modifications in tumor associated fibroblasts may lead to more effective treatments in patients with breast tumors without toxicity to normal tissues." (PMID 23977064, 2013). "As a result, in mice, the deletion of Ets2 in macrophages leads to exacerbated cytokines production upon a TLR challenge, but reduced lung metastasis in breast tumour models." (PMID 39019900, 2024). "However, in breast tumor cells, despite the promoter being accessible as indicated by H3K4me3 marks, ATAC-seq, and RNA Pol II occupancy, ETS2 transcription was paused." (PMID 39796183, 2025).
glioblastoma (5 papers, 2015 to 2025). The most malignant astrocytic tumor (WHO grade IV). "ID2 and ETS2 genes were found to be expressed by the tumour-associated microglia isolated from human glioblastoma tumour biopsies." (PMID 39019900, 2024).
inflammatory bowel disease (5 papers, 2023 to 2025). A spectrum of small and large bowel inflammatory diseases of unknown etiology. "ETS2—which is associated with inflammatory bowel disease, ankylosing spondylitis, primary sclerosing cholangitis and Takayasu’s arteritis—is a central regulator of human inflammatory macrophages." (PMID 38839969, 2024). "Patients with inflammatory bowel disease (IBD) often carry another risk SNP, the rs2836754 allele (T), which leads to disease-specific ETS2-SE activation both in IBD and CRC since TF MECOM prefers binding at the T allele over C in this region." (PMID 38542080, 2024). "Conversely, overexpressing ETS2 induced a striking, dose-dependent upregulation of the same pro-inflammatory pathways and induced a pathogenic state that closely resembled the macrophage phenotype seen in diseased tissue from conditions such as inflammatory bowel disease (IBD)." (PMID 40227609, 2025). "The ETS2 gene, a member of the ETS (E26 transformation-specific) family of transcription factors, plays a critical role in the regulation of immune responses, epithelial barrier integrity, and fibrosis, all of which are central to the pathogenesis of inflammatory bowel disease (IBD)." (PMID 40922284, 2025).
melanoma (5 papers, 2011 to 2022). A malignant, usually aggressive tumor composed of atypical, neoplastic melanocytes. "Pearson regression results from 4 different melanoma databases showed that SOX10 and USF2 were positively correlated with the expression of SMARCA4, yet TBX15 and ETS2 were negatively correlated with the expression of SMARCA4." (PMID 36317703, 2022). "In particular, ELK3, ETS1, ETV1, ETV4, ETV5, and SPI1 were significantly upregulated in melanoma, whereas EHF, ELF3, ELF5, ERG, ETS2, ETV7, and SPDEF were significantly downregulated in the tumor." (PMID 33424867, 2020). "In addition, no studies have reported on the expression and function of ELK3, ETV5 ELF3, ELF5, ETS2, and SPDEF in melanoma." (PMID 33424867, 2020). "USP9X effects on ETS-1 stability appear not to extend to ETS-2, because USP9X knockdown in melanoma cells decreased ETS-1 protein levels but left ETS-2 unaffected." (PMID 34066106, 2021). "We then considered the possibility that this Ets-dominant negative protein interferes with other members of the ETS family, although we never observed any significant modulation of ETS-2, the closest member to ETS-1, in our melanoma samples (data not shown)." (PMID 21711453, 2011).
non-small cell lung carcinoma (5 papers, 2016 to 2025). A group of at least three distinct histological types of lung cancer, including non-small cell squamous cell carcinoma, adenocarcinoma, and large cell carcinoma. "In non-small cell lung cancer, SE promote TGFβ-induced EMT by enhancing the expression of EMT-related transcription factors, while a BRD4-specific inhibitor JQ1 can inhibit SE-driven transcription of ETS2, HNF4A, JUNB, and other genes, resulting in the obstruction of EMT process." (PMID 39915455, 2025).
pancreatic cancer (5 papers, 2016 to 2025). "GEPIA confirmed that ETS2 was highly expressed in pancreatic cancer and positively correlated with the expression of NAT10 and PD-L1." (PMID 41203621, 2025). "In conclusion, NAT10 promotes pancreatic cancer progression and immune evasion by regulating the ETS2-PD-L1 axis and stabilizing KRT8 mRNA, highlighting its potential as a therapeutic target for overcoming immunotherapy resistance." (PMID 41203621, 2025). "Western blotting analysis revealed that ETS2 knockdown reduced the protein levels of both NAT10 and PD-L1 in pancreatic cancer cells." (PMID 41203621, 2025). "It is noteworthy that transcription factors, such as ETS2, JUN, and ELK1, were upregulated in the KRAS mutated CRC, but not in lung and pancreatic cancers." (PMID 33982211, 2021).
Alzheimer disease (4 papers, 2019 to 2024). A progressive, neurodegenerative disease characterized by loss of function and death of nerve cells in several areas of the brain leading to loss of cognitive function such as memory and language. "The expression levels of the genes for APP (Alzheimer’s disease marker), DYRK1A, DSCR1 (Down syndrome critical region 1), ETS2, and SOD1, all of which are located on chromosome 21, are dysregulated in trisomic cells." (PMID 34433490, 2021).
diabetes mellitus (4 papers, 2009 to 2024). A metabolic disorder characterized by abnormally high blood sugar levels due to diminished production of insulin or insulin resistance/desensitization. "The data of the present study demonstrate that increased nuclear DNA-binding activities of ETS1 and ETS2 transcription factors are crucial determinants of diabetes- and high glucose-induced reduced number of VPC." (PMID 19225563, 2009). "Our results expand our understanding of mechanisms of inappropriate regulation of miR-124a involved in processes leading to human disease such as diabetes mellitus, and imply a series of new ETS2 functions, and support future work in exploring this pathway in vivo." (PMID 31754329, 2019).